UGT2B17 (UDP glucuronosyltransferase family 2 member B17)
Diseases named in the same sentence as UGT2B17 in open-access papers (continued):
Sharing a sentence is not in itself a finding about the gene and the disease.
leukaemia (5 papers, 2018 to 2023). "In pediatric leukemia, certain SNPs, such as UGT2B17, have been correlated with treatment toxicity, neurocognitive outcomes, and overall mortality." (PMID 37878192, 2023). "FUT4 is increased in leukaemia, gastric, breast and colorectal cancer; UGT2B17 is increased in endometrial cancer; POFUT1 is increased in glioblastomas and oral squamous cell carcinoma, and MAN2A1 is decreased in glioblastoma." (PMID 30038662, 2018). "Elevated expression of UGT2B17 also occurs in the treatment of leukemia with fludarabine or ibrutinib, which may also suggest the exists of drug resistance." (PMID 36741721, 2022). "For example, it has been shown that UGT2B17 can glucuronidate prostaglandin E2 (PGE2) thereby affecting the frontal proliferation and migratory capacity of leukemia cells." (PMID 36741721, 2022).
prostate tumor (4 papers, 2014 to 2026). "A number of studies have been done to elucidate the possible association between the UGT2B17 null genotype and risks for different types of tumor in diverse populations, such as prostate tumors, lung tumors, breast tumors, and colorectal tumors." (PMID 24802609, 2014). "In one study the expression levels of UGT2B17 and B15 in prostate tumor samples from ADTh treated patients were compared to expression levels in patients that were untreated or diagnosed as benign prostatic hyperplasia (BPH)." (PMID 28673330, 2017). "Therefore, we scored the total UGT2B17 signal using Aperio ImageScope and found that UGT2B17 expression was 1.5- to 2.8-fold higher in primary prostate tumors compared with benign prostate tissue and 1.4- to 3-fold higher in CRPC than in primary tumors." (PMID 41343245, 2026). "An individuals' susceptibility to breast, lung, or prostate tumors might be associated with the UGT2B17 null genotype, which does not express protein." (PMID 24802609, 2014). "Similar to normal prostate tissue, prostate tumours expressed several UGT2B mRNAs, including UGT2B17 but also UGT2B4, UGT2B7, UGT2B10, UGT2B11, UGT2B15 and UGT2B28." (PMID 32047296, 2020). "Paradoxically, UDP glucuronosyltransferase family 2 member B17 (UGT2B17), the key enzyme responsible for androgen catabolism in prostate tumor cells, is upregulated in therapy-resistant tumors, though its role in tumor progression remains unclear." (PMID 41343245, 2026).
hip fracture (3 papers, 2013 to 2021). Traumatic or pathological injury to the hip in which the continuity of either the femoral head, femoral neck, intertrochanteric or subtrochanteric regions is broken. "The frequency difference of UGT2B17 homozygous deletion across populations, therefore, is consistent with the lower risk of osteoporotic hip fracture found in Asian as compared to Caucasian populations." (PMID 25118596, 2014).
colorectal cancer (2 papers, 2018 to 2021). A primary or metastatic malignant neoplasm that affects the colon or rectum. "The most common example is UGT2B17, where CNV has been correlated with pancreatic, prostate, and colorectal cancer, in addition to other diseases related to differential testosterone concentrations." (PMID 33420067, 2021).
lung carcinoma (2 papers, 2015 to 2016). "Therefore, this UGT2B17-deletion may increase an individual’s susceptibility to tobacco-related cancers, e.g., lung cancer." (PMID 25886176, 2015). "The frequency of UGT2B17-deletion was only about 10 to 15% among general Caucasian population or Caucasian with lung cancer." (PMID 25886176, 2015).
lymph node metastasis (2 papers, 2013 to 2015). "Interactions between smoking and each of 11 variables—age, gender, alcohol drinking status, the primary sites of tumors, tumor grades, stages, the number of lymph node metastasis, UGT2B17-deletion, CDKN2A-SCNAs, p16 (+), and a combination of UGT2B17-deletion and p16 (+)—were assessed." (PMID 25886176, 2015).
Obesity (2 papers, 2018 to 2025). Accumulation of substantial excess body fat. "Similar to the elevated levels of sex steroids in UGT2B17 KO, higher levels of phosphatidylcholine derivatives consistently correlated with a reduced risk of obesity, diabetes and heart failure, whereas higher levels of sphingolipids were associated with an increased risk of obesity and arthritis." (PMID 40264209, 2025). "Our findings for UGT2B17 KO males suggest favorable metabolic health and possibly reduced prevalence of obesity, diabetes and hypertension." (PMID 40264209, 2025). "Similar results were observed among female individuals lacking UGT2B17, with significant associations with obesity, hypertension and diabetes." (PMID 40264209, 2025).
Autoimmunity (1 paper, 2025). The occurrence of an immune reaction against the organism's own cells or tissues. "The UGT2B28 single-copy state (CN = 1) was enriched in cases but is also relatively common in the general population, and the locus overlaps the UGT2B17 region, so specificity for autoimmunity remains uncertain." (PMID 41465179, 2025).
breast tumors (1 paper, 2014). "One study that extracted DNA both from blood and paraffin-embedded tissue specimens showed an association between the UGT2B17 null genotype and breast tumors." (PMID 24802609, 2014).
Cirrhosis (1 paper, 2025). A chronic disorder of the liver in which liver tissue becomes scarred and is partially replaced by regenerative nodules and fibrotic tissue resulting in loss of liver function. "Among all, the top 5 hub genes identified for NAFLD vs. control were CXCL9, NOS2, SERPINE1, FABP4, and LPL, whereas AKR1D1, UGT2B17, CYP26B1, LIPC, and DGAT2 were identified as the top 5 hub genes for the NAFLD vs. cirrhosis group." (PMID 40365443, 2025). "Additionally, the top 5 biological functional hub genes in NAFLD vs. control (CXCL9, NOS2, SERPINE1, FABP4, and LPL) and NAFLD vs. cirrhosis (AKR1D1, UGT2B17, CYP26B1, LIPC, and DGAT2) groups were identified through PPI analysis among lipid, immune, and metabolism dysregulated genes." (PMID 40365443, 2025).
esophageal tumors (1 paper, 2019). "As the loss of UGT2B17 alleles results in lower testosterone levels, it is tempting to speculate that the expression of UGT2B17 may serve as a key contributor which defines the histological route for the development of esophageal tumors." (PMID 31164411, 2019).
gastric cancer (1 paper, 2022). A primary or metastatic malignant neoplasm involving the stomach. "Four distributed genes ACOT1, GSTM1, SIGLEC14, and UGT2B17 showed extremely high frequencies of absence in the gastric cancer population." (PMID 36109518, 2022). "Genes ACOT1, GSTM1, SIGLEC14, and UGT2B17 are highly absent in Chinese Hans, even in the Asian population, compared to the non-Asian healthy population, suggesting a potential association for the high incidence of gastric cancer in the Asian population." (PMID 36109518, 2022). "Genes ACOT1, GSTM1, SIGLEC14 and UGT2B17 are identified as highly absent genes in gastric cancer population." (PMID 36109518, 2022).
inflammatory bowel disease (1 paper, 2020). A spectrum of small and large bowel inflammatory diseases of unknown etiology. "They overlap genes which have been associated with such disease; such as UGT2B17 (UDP Glucuronosyltransferase Family 2 Member B17) associated with the bone mineral density quantitative trait locus and IRGM (Immunity-related GTPase family M protein) associated with inflammatory bowel disease." (PMID 32272904, 2020).
male infertility (1 paper, 2018). The inability of the male to effect fertilization of an ovum after a specified period of unprotected intercourse. "The UGT2B17 gene, a sex steroid-metabolizing gene, has been associated with male infertility and impaired spermatogenesis." (PMID 29616079, 2018).
metastatic prostate carcinoma (1 paper, 2021). A carcinoma that arises from the prostate gland and has spread to other anatomic sites. "For example, previous work shows that UGT2B17 and UGT2B28 are overexpressed in advanced and metastatic prostate cancer and associate with poor outcomes." (PMID 34503303, 2021).
cancer (18 papers, 2013 to 2024). A tumor composed of atypical neoplastic, often pleomorphic cells that invade other tissues. "We focused on portraying the metabolic features of cancer cells associated with overexpression of the adverse metabolic marker glycosyltransferase (UGT2B17)." (PMID 38037464, 2023). "UGT2B17 is a frequently reported gene in various cancers and is frequently associated with polymorphism deletion." (PMID 27806083, 2016). "The objective was to evaluate UGT2B17 protein expression in primary tumours in relation to hormone levels, disease characteristics and cancer evolution." (PMID 32047296, 2020). "It is plausible that UGT2B17 influences intracellular levels of hormone-like signaling molecules involved in the regulation of gene expression, with subsequent impacts on cancer cell growth and survival." (PMID 31334126, 2019). "We further analyzed UGT2B15, UGT2B17, and UGT2B28 to determine whether they were genetically linked to cancer." (PMID 39457450, 2024). "Building on these observations and given their wide tissue distribution, we hypothesised that UGT2B17 and UGT2B28 deficiencies induce a significant rewiring of the systemic metabolome to which cancer cells are exposed, driven by several tissues." (PMID 36347965, 2023). "One mechanism by which UGT2B17 may modify cancer cell behavior may be through inactivation of PGE2, thereby altering homeostatic levels of PGE2 and gene expression related to PGE2 synthesis, transport and action." (PMID 31334126, 2019). "Likewise, the population PK investigation of the recently approved anti-cancer drug belzutifan revealed that the dual UGT2B17 and CYP2C19 poor metabolizers are expected to show a 3.2-fold AUC, which could lead to adverse events." (PMID 39204377, 2024). "UGT2B17 belongs to a superfamily that comprises 22 enzymes responsible for the conjugation of a vast array of molecules ranging from endogenous metabolites, such as steroids to anti‐cancer agents, linking them to glucuronic acid, which leads to their inactivation." (PMID 38037464, 2023). "Alternative splicing events, potential post-translational modifications and/or interactions with specific and unidentified binding partners, may partly explain the shift in subcellular distribution of UGT2B17 from the nucleus in normal cells to the cytoplasm observed in cancer cells." (PMID 32047296, 2020). "Given the important role of these enzymes in cancer pathology, we hypothesized that UGT2B15 and UGT2B17 are novel targets for inhibitory regulation by IGF1." (PMID 35626664, 2022). "Deletions of UGT2B17, PRSS2/PRSS3P2, and GSTT1/GSTTP2 were frequently observed in S1, and other reports indicate that these genes are frequently deleted in cancer cells." (PMID 27806083, 2016).
tumor (16 papers, 2014 to 2026). "Conversely, both UGT2B17 cytoplasmic and nuclear staining in primary tumours were associated with node-positive disease at surgery, and nuclear staining with the development of metastasis during follow-up." (PMID 32047296, 2020). "UGT2B17 expression in primary tumours influences the steroidome, and is associated with relevant clinical outcomes, such as BCR and metastasis." (PMID 32047296, 2020). "Identification of a UGT2B17 deletion polymorphism has attracted studies to evaluate the association between the UGT2B17 deletion polymorphism and tumor risk in diverse populations." (PMID 24802609, 2014). "The analysis included 14 studies from 10 publications on UGT2B17 deletion polymorphism and tumor risk, including 5,732 cases and 5,112 controls." (PMID 24802609, 2014). "Conclusively, our results indicate that individuals with a UGT2B17 deletion polymorphism were associated with tumor risks (OR = 1.29, 95% CI = 1.03–1.63, P<0.001) in a recessive model." (PMID 24802609, 2014). "Besides NF2, the same study found that several other tumor suppressors, including OPCML, Cav-1, and UGT2B17, showed a loss of tumor suppressive effects." (PMID 39796693, 2024). "A deletion polymorphism in UGT2B17 is thought to suppress tumor growth, which could contribute to an overall greater prognosis and reduced chance of relapse." (PMID 37878192, 2023). "Although the number of metastatic events were limited, UGT2B17 protein expression in primary tumours was further associated with the development of metastasis during follow-up, which represents a surrogate marker of PCa-specific survival in this patient population." (PMID 32047296, 2020). "Targeting the newly identified UGT2B17 functions using a combination of inhibitors reduced tumor growth in therapy-resistant tumor models, highlighting a promising therapeutic strategy." (PMID 41343245, 2026). "UGT2B17 is involved in the metabolism of steroid hormones and xenobiotics, which can alter the tumor microenvironment." (PMID 39910169, 2025). "The mean UGT2B17 cytoplasmic expression is 6% (95% CI: 3–9) vs 19% (95% CI: 14–24) in the AR < 25% vs AR ≥ 25% tumours, respectively (P < 0.0019)." (PMID 32047296, 2020). "When using an AR cut-off value of 25%, the mean UGT2B17 nuclear expression is 38% (95% CI: 29–46) vs 57% (95% CI: 50–64) in the AR < 25% vs AR ≥ 25% tumours, respectively (P = 0.0003)." (PMID 32047296, 2020). "In primary tumours, a weak correlation was observed between UGT2B17 nuclear and cytoplasmic staining (rs = 0.14; P = 0.025)." (PMID 32047296, 2020). "In conclusion, UGT2B17 is a crucial enzyme involved in steroid catabolism in PCa, and its tumour expression level appears to influence the outcomes of PCa patients." (PMID 32047296, 2020). "CNAs of gene SNORA26 (3p21.1) and UGT2B17 (4q13.2) were predominantly determined in G1 (Fisher’s exact test p<0.00811) and in G3 tumours (Fisher’s exact test p<0.137), respectively." (PMID 28486536, 2017). "Here, we report that UGT2B17 has tumor-promoting functions beyond androgen catabolism." (PMID 41343245, 2026). "UGT2B17 inactivates the signaling lipid prostaglandin E2 by conjugation to glucuronic acid and downregulates the prostaglandin signaling pathway, which displays tumor suppressor functions in B-cells." (PMID 37174695, 2023). "This adds to the previously documented inactivation of prostaglandin E2 by UGT2B17-mediated glucuronidation that abrogated the tumor suppressor functions of PGE2 in B-cells and exposed an enzymatic mechanism by which UGT2B17 might influence CLL progression." (PMID 37174695, 2023). "Pre-clinical studies in mouse xenograft models show that UGT2B17 overexpression promotes androgen-independent tumor progression via a pathway that may involve tyrosine-protein kinase Src." (PMID 34503303, 2021).
tumor (continued). "UGT2B17 expression in primary tumours was associated with node-positive disease at RP and linked to circulating levels of 3α-diol-17 glucuronide, a major circulating DHT metabolite produced by the UGT2B17 pathway." (PMID 32047296, 2020). "In primary tumours, weak but positive correlations were observed between the AR and cytoplasmic (rs = 0.33; P < 0.0001; r2 = 12.4%) and nuclear (rs = 0.20; P = 0.005; r2 = 3.76%) UGT2B17 staining." (PMID 32047296, 2020). "Studies have showed that UGT2B17 may contribute to the progress of chronic lymphatic leukemia and has an impact on antineoplastic drug metabolism in tumor cells." (PMID 24802609, 2014). "In conclusion, our meta-analysis did not demonstrate a significant role of the UGT2B17 deletion polymorphism and tumor susceptibility (OR = 1.118, 95%CI = 0.938–1.332, P>0.1)." (PMID 24802609, 2014). "Recent studies indicate that men exhibited a 4-fold higher UGT2B17 expression level than women, and these findings are indicate that this increase gene expression may play a greater role in reducing tumor risks in men than in women." (PMID 24802609, 2014). "Additional studies are required to further evaluate whether the role of UGT2B17 in PCa extends beyond androgen catabolism and signalling, and to decipher the regulatory mechanisms prevailing in normal prostate, primary PCa tumours and throughout metastatic dissemination." (PMID 32047296, 2020). "If UGT2B15 and UGT2B17 are important determinants of the availability of bioactive androgens in the tumor micro milieu in vivo, patients with low ADRB2 expression may have a lower response to androgen-deprivation therapy through lowered UGT2B15 and UGT2B17 protein levels." (PMID 26646591, 2016). "Of note, from RCC42, three deep deletions, UGT2B17, OR4P4 and CES1P1 were consistently observed in both parental tumor and organoid lines." (PMID 38923304, 2024). "To evaluate the relationship between the expression of UGT2B17 and ZAP70, we initially studied the GSE21029 data set that provides gene expression from purified tumor cells obtained concurrently from blood, bone marrow, and lymph nodes of CLL patients." (PMID 37174695, 2023). "Four genes (UGT2B17, SST, CRYGB, and THRSP) were downregulated in tumor samples, whereas eighty genes were increased." (PMID 36785673, 2023). "Immunohistochemical staining of tumor tissue from the xenograft study using anti-UGT2B15 and anti-UGT2B17 antibodies showed that the phenotypic differences between shCtrl and shADRB2-2 cells were maintained also after castration." (PMID 26646591, 2016). "UGT2B17 is also expressed in primary and CRPC tumors, where its in situ tumor activity could also influence the maintenance of tumor androgen levels." (PMID 29210989, 2017). "This mutual regulation presents a paradox that androgen pathway inhibition and its consequential UGT2B17 upregulation should, theoretically, eliminate androgens completely in PCa cells, leading to irreversible tumor suppression and no CRPC progression, if the tumors rely on androgens to progress." (PMID 41343245, 2026). "Blocking non-androgen catabolic function of UGT2B17 inhibits PCa cell growth and tumor progression." (PMID 41343245, 2026). "In the current study, the results suggest that UGT2B17 overexpression was associated with BCR, which may be an indication overexpression may be a marker for tumor progression to CRPC independent of intracellular glucuronide levels." (PMID 28673330, 2017).